FTCDNL1 (formiminotransferase cyclodeaminase N-terminal like)
Synonyms: FONG
Tractability: Antibody: UniProt predicts a signal peptide or a membrane-spanning region.
Gene: Protein-coding gene on chromosome 2 (199,760,544 to 199,851,207, reverse strand). Ensembl gene ENSG00000226124.
Subcellular location (Human Protein Atlas): Vesicles
Gene Ontology:
Molecular function: transferase activity; folic acid binding
Homologues: Orthologues: chimpanzee FTCDNL1 (98% identical), macaque FTCDNL1 (93% identical), tropical clawed frog ftcdnl1 (59% identical), zebrafish ftcdnl1 (51% identical). Paralogues in human: FTCD (25% identical).
Diseases named in the same sentence as FTCDNL1 in open-access papers:
FTCDNL1 is named in the same sentence as 5 diseases in open-access papers, as found by Europe PMC text mining. Sharing a sentence is not in itself a finding about the gene and the disease. The quoted sentences say what the papers report.
osteoporosis (6 papers, 2011 to 2025). A condition of reduced bone mass, with decreased cortical thickness and a decrease in the number and size of the trabeculae of cancellous bone (but normal chemical composition), resulting in increased fracture incidence. "Polymorphisms of the FONG (FTCDNL1) gene (rs7605378) were reported to be associated with the risk of osteoporosis in a Japanese population." (PMID 26492493, 2015). "In the GWAS in Japanese, the SNP rs7605378 was found to be the most significant SNP in the FTCDNL1 gene locus and the minor allele was associated with a decreased risk of having osteoporosis." (PMID 26492493, 2015). "In summary, our studies confirmed the association of the FTCDNL1 SNPs and the risk of having osteoporosis." (PMID 26492493, 2015). "Association analysis between FTCDNL1 single-nucleotide polymorphisms and osteoporosis susceptibility in females." (PMID 26492493, 2015). "Our findings provide evidence that rs10203122 in FTCDNL1 is associated with a susceptibility to osteoporosis." (PMID 26492493, 2015). "FTCDNL1 played an important role in bone metabolism and in the development of osteoporosis in humans." (PMID 40965274, 2025). "Consistent with a published GWAS in a Japanese sample, polymorphisms in FTCDNL1 gene region were associated with a decreased risk of having osteoporosis in our study in a Taiwanese sample, suggesting this gene may be involved in the pathogenesis of osteoporosis." (PMID 26492493, 2015). "Haplotype frequencies of the FTCDNL1 gene in controls and patients with osteoporosis." (PMID 26492493, 2015). "Another obvious case and not tagged as potential non-coding is FTCDNL1, an uncharacterized five-exon gene related to osteoporosis." (PMID 40996716, 2025). "Another obvious case and not tagged as potential non-coding is FTCDNL1, an uncharacterised five exon gene related to osteoporosis." (PMID 39713347, 2024).
schizophrenia (2 papers, 2021 to 2023). A major psychotic disorder characterized by abnormalities in the perception or expression of reality. "The SNP rs281785 resides approximately 33 kb upstream of TSS of FTCDNL1 and recently a causal relationship between increased schizophrenia risk and reduced FTCDNL1 expression was reported." (PMID 37906604, 2023).
FTCDNL1 also shares sentences with these, for which no sentence is quoted: amyotrophic lateral sclerosis (1 paper); Cluster headache (1); Parkinson disease (1).